TRIM25 (tripartite motif containing 25)
Diseases named in the same sentence as TRIM25 in open-access papers (continued):
Sharing a sentence is not in itself a finding about the gene and the disease.
breast carcinoma (continued). "Our findings demonstrate that targeting the TRIM25/BRD7/YB1/Bcl-2 signal axis might be a potential therapeutic strategy for the treatment of breast cancer." (PMID 41315221, 2025). "By employing gene set enrichment analysis, TRIM25 has, e.g., been identified as a key transcriptional regulator of metastasis-related breast cancer gene networks and knockdown of TRIM25 drastically impaired the expression of mainly those genes which are related to migration and invasion." (PMID 39851496, 2025). "The overexpression of TRIM25 resulted in an increased percentage of BC cells in the G2/M phase compared with the control, while the inhibition of TRIM25 decreased the percentage of cells in the G2/M phase in breast cancer cells." (PMID 41315221, 2025). "Meanwhile, we confirmed that the expression of TRIM25 in breast cancer patients was significantly upregulated, and its expression level positively correlated with clinical stages and poor prognosis of BC patients, indicating that TRIM25 is a potential oncogene in breast cancer." (PMID 41315221, 2025). "Therefore, we suspect that BRD7 mediates the process of TRIM25 promoting the occurrence and development of breast cancer and PTX resistance." (PMID 41315221, 2025). "Moreover, TRIM25 has been proven to be an important determinant of the breast cancer malignant process and an effective prognostic factor for breast cancer patients." (PMID 41315221, 2025). "However, the precise functions and molecular mechanisms of TRIM25 in breast cancer pathogenesis and PTX chemotherapy resistance remain to be fully elucidated." (PMID 41315221, 2025). "However, silencing IGF2BP3 expression suppresses breast cancer cell proliferation by reducing tripartite motif-containing 25 (TRIM25) expression." (PMID 35677634, 2022). "Estrogen-responsive finger protein (Efp), a member of the TRIM family proteins, also known as TRIM25, was originally identified as a protein induced by estrogen and plays critical roles in promoting endocrine-related cancers, including breast cancer, endometrial cancer, and prostate cancer." (PMID 35954308, 2022). "The increased expression of TRIM25 in breast cancer is related to unfavorable overall survival." (PMID 33506106, 2021). "A comprehensive study identified TRIM25 as a key gene in regulating TN breast cancer metastasis." (PMID 34193143, 2021). "Overexpressed miR-3614-3p inhibits the growth of breast carcinoma cells via downregulating TRIM25." (PMID 33506106, 2021). "IGF2BP3 served as an antagonism could inhibit miRNA-3614 maturation, mediately resulted in preventing breast cancer cell growth through downregulating TRIM25." (PMID 34338136, 2021). "In addition, TRIM25 has been reported to be a global transcriptional regulator positioned at the center of breast cancer metastasis-related transcriptional networks." (PMID 32826889, 2020). "Recently, TRIM25 has been shown to be a master regulator of breast cancer metastasis." (PMID 29117863, 2017). "Interestingly, upregulated TRIM25 expression is usually detected in many types of tumor cells, especially in hormone-responsive tumors, such as breast cancer, prostate cancer, ovarian cancer, and endometrial cancer, because of its estrogen-responsive characteristics." (PMID 40431746, 2025). "Therefore, we speculated that TRIM25 participated in the malignant progression of breast cancer by regulating the BRD7/YB1 axis." (PMID 41315221, 2025). "Therefore, interference with single components of the autophagic UBC12/TRIM25/TFEB axis may offer a further pharmacological approach to restore the sensitivity of breast cancer and probably other cancer types to chemotherapy-induced cell death." (PMID 39851496, 2025).
breast carcinoma (continued). "Furthermore, in breast cancer, IGF2BP3 could inhibit miRNA-3614 maturation and protect TRIM25 mRNA from degradation to promote breast cancer cell proliferation." (PMID 37407973, 2023). "Similarly, TRIM25 was reported as overexpressed in breast cancer cells." (PMID 36980857, 2023). "Consistently, data analysis from TCGA cohort also revealed higher TRIM25 expression in HCC patients was associated with poor clinical outcome as well as shorter disease-free survival times, which also observed in patients with breast cancer and lower grade glioma." (PMID 31953436, 2020). "Although results from the mass spectrometry indicated a relatively low caspase-2 mRNA-binding affinity, we chose this candidate because TRIM25 has previously been reported as a key determinant of breast cancer metastasis, suggesting that it could also exert a tumorigenic role in colon carcinoma." (PMID 31842382, 2019). "By analyzing the expression of TRIM25 across different clinical stages, we found that its expression in stage III and IV breast cancer tissues was higher than in stage I and II tissues, indicating a positive correlation with disease stage." (PMID 41315221, 2025). "Herein, we further clarify the clinical value and significance of the expression of TRIM25 and BRD7 in patients with breast cancer." (PMID 41315221, 2025). "Additionally, TRIM25 decreased the protein stability of BRD7 through the ubiquitin proteasome pathway by increasing the K48-linked ubiquitination of BRD7 at the K119 site, and then activated the YB1/Bcl-2 signal axis, thus mediating malignant progression and PTX resistance of breast cancer." (PMID 41315221, 2025). "Our results confirmed that TRIM25 was involved in the malignant progression of breast cancer and PTX resistance, and that TRIM25 participates in the regulation of ubiquitination level and protein degradation of BRD7 through the ubiquitin-proteasome pathway." (PMID 41315221, 2025). "Taken together, the present study shows that TRIM25 works as an oncogene and promotes PTX resistance in breast cancer." (PMID 41315221, 2025). "To better understand the potential clinical correlation between TRIM25 and BRD7, we detected the expression of TRIM25 and BRD7 in 34 normal breast tissues and 219 breast cancer biopsies." (PMID 41315221, 2025). "Collectively, our data revealed that BRD7 is essential for TRIM25-induced malignant progression and PTX chemoresistance of breast cancer cells." (PMID 41315221, 2025). "Moreover, we further validated that high TRIM25 expression predicts poor prognosis of BC patients, and a combination of TRIM25 and BRD7 expression is an effective marker for the prognosis of breast cancer." (PMID 41315221, 2025). "To systematically determine the impact of TRIM25 on p300-depedent gene expression in yet another context, we performed RNA-seq in the estrogen receptor α-dependent breast cancer cell line MCF7, in which TRIM25 was knocked-out by CRISPR/Cas9." (PMID 37770115, 2023). "Consistently, a similar effect was observed in a variety of tumor cells including human hepatocellular carcinoma Huh7, breast cancer MCF7 and osteosarcoma U2OS cells, indicating a common mechanism for TRIM25 in response to ER stress in various tumors." (PMID 31953436, 2020). "Overall, these data identified that the TRIM25/BRD7 axis could guide the early diagnosis and treatment in breast cancer patients and provide a potential therapeutic target for breast cancer therapy." (PMID 41315221, 2025). "Altogether, this study verified the mechanism by which the TRIM25/BRD7/YB1/Bcl-2 axis is involved in the malignant progression and PTX resistance of breast cancer, providing a novel insight into BC development and potential targets for improving the PTX therapeutic resistance." (PMID 41315221, 2025). "Furthermore, co-IP experiments also validated the endogenous interactions of TRIM25 with UBC12 and TFEB in breast cancer cells." (PMID 38926803, 2024).
breast carcinoma (continued). "Here we demonstrate that the mRNA levels of TRIM25 are upregulated in a variety of cancer types including HCC and that upregulation of TRIM25 correlated with poor clinical outcome in patients with HCC as well as breast cancer and low grade glioma." (PMID 31953436, 2020). "Consequently, these findings reveal that TRIM25 promotes ubiquitination-mediated degradation of BRD7 and promotes breast cancer progression and paclitaxel resistance via the YB1-Bcl-2 axis, which provides a new prognostic predictor and therapeutic target for breast cancer." (PMID 41315221, 2025). "Accordingly, targeting the TRIM25/BRD7/YB1/Bcl-2 signal axis may be a potential molecular target for early diagnosis of breast cancer and promoting the sensitization of PTX in clinical breast cancer patients." (PMID 41315221, 2025). "However, the functions and mechanisms of TRIM25 in the malignant progression and PTX resistance of breast cancer, as well as the regulatory relationship between TRIM25 and BRD7, have not been determined." (PMID 41315221, 2025). "Furthermore, high expression of TRIM25 was found in clinical breast cancer tissues compared to noncancerous breast tissues, which was positively associated with poor prognosis in BC patients." (PMID 41315221, 2025). "The expression of TRIM25 was negatively correlated with BRD7 expression, and the combined expression of TRIM25 and BRD7 might be a potential molecular marker for the prediction of malignant progression and prognosis of breast cancer." (PMID 41315221, 2025). "IGF2BP3 accelerates the proliferation of breast cancer cells not only by regulating the target of the corresponding mRNA but also by competitively binding with miR-3614-3p to the 3’UTR of the host gene TRIM25 and protecting TRIM25 mRNA from miR-3614-mediated degradation." (PMID 36052258, 2022). "Thus, we have shown that TRIM25 negatively regulates the stability of BRD7 protein through the ubiquitin-proteasome pathway, and confirmed the direct binding domains of TRIM25 and BRD7, which provide the molecular basis for further development of targeted therapy for the treatment of breast cancer." (PMID 41315221, 2025).
hepatocellular carcinoma (25 papers, 2019 to 2026). A malignant tumor that arises from hepatocytes. "TRIM25 expression was found positively associated with NRF2 expression in hepatocellular carcinoma, mechanistically, TRIM25 directly targeted Keap1 by ubiquitination and degradation, leading to NRF2 activation." (PMID 35087512, 2021). "TRIM25 expression is positively associated with Nrf2 expression and negatively with Keap1 expression in hepatocellular carcinoma (HCC) xenografts and specimens." (PMID 31953436, 2020). "Previous studies have shown that TRIM25 promotes the survival and growth of hepatocellular carcinoma cells through targeting the Keap1‒Nrf2 pathway; Trim25 inhibits ITPKB degradation and imparts TMZ resistance in glioblastoma through ROS homeostasis." (PMID 40796546, 2025). "TRIM25 inhibits the invasion and migration of hepatocellular carcinoma cells by targeting the ubiquitination and degradation of Metastasis-Associated 1 (MTA1) protein." (PMID 41315221, 2025). "Here, we describe a regulatory process for vtRNA1-1 stabilization mediated by the newly identified interacting proteins, TRIM21 and TRIM25, in human hepatocellular carcinoma (HCC) cells." (PMID 40096176, 2025). "In hepatocellular carcinoma, TRIM25 regulates endoplasmic reticulum homeostasis and mitigates oxidative stress by mediating the ubiquitination and degradation of Keap1." (PMID 38303029, 2024). "In another investigation, Liu and colleagues demonstrated that by focusing on the Keap1-Nrf2 pathway, TRIM25 enhances hepatocellular carcinoma cell survival and proliferation." (PMID 39286246, 2024). "TRIM25 has been reported to promote cell survival by ubiquitinating and degrading Keap1 in hepatocellular carcinoma." (PMID 35871160, 2022). "TRIM25 contributes to the survival and the growth of hepatoma cells via targeting the Keap1-Nrf2 pathway, and highly expressed TRIM25 predicts the unfavorable prognosis of patients with liver carcinoma." (PMID 33506106, 2021). "Moreover, we found that TRIM25 expression is associated with hepatocellular carcinoma (HCC) progression and high TRIM25 expression correlates with poor patient survival in HCC." (PMID 32984318, 2020). "It is noteworthy that while the 14-3-3ε isoform was shown to form inducible complexes with TRIM25 in Sendai virus infected hepatoma cells, 14-3-3η and 14-3-3σ exhibited constitutive TRIM25 binding." (PMID 31710640, 2019). "We then assessed TRIM25 expression through a human hepatocellular carcinoma (HCC) TCGA data set." (PMID 32826889, 2020). "In hepatocellular carcinoma (HCC), tripartite motif-containing 25 (TRIM25) serves as a downstream effector of the ER stress response, specifically activating the IRE1-JNK signaling branch within the UPR signaling network." (PMID 41209558, 2025). "In hepatocellular carcinoma (HCC), TRIM25 has been found to target and degrade Keap1, consequently activating Nrf2 and fostering HCC cell proliferation by modulating the UPR signaling pathway and ERAD." (PMID 39080273, 2024). "For example, TRIM25 activates NRF2 and promotes the progression of hepatocellular carcinoma, regulates the stability of EZH2, thereby promoting the resistance of colorectal cancer to oxaliplatin." (PMID 38926803, 2024). "Some studies suggest that TRIM25 is an E3 ligase that interacts with and degrades MTA-1 protein, which is one of the important mediators of metastatic progression in hepatocellular carcinoma." (PMID 36360326, 2022). "Here we reported a new regulated axis for HBV related hepatocellular carcinoma, namely, the lncRNA XIST-miR-192/TRIM25 axis." (PMID 33858324, 2021). "Additionally, miR-192 targets TRIM25 to inhibit proliferation and migration in hepatitis B virus-related hepatocellular carcinoma, and targets SLC39A6 to reduce tumor metastasis in hepatocellular carcinoma cells." (PMID 40087755, 2025).
prostate carcinoma (19 papers, 2015 to 2025). A carcinoma that arises from epithelial cells of the prostate gland. "Furthermore, we demonstrate that knockdown of TRIM25 with the same siRNAs causes increased protein levels of ERG in 22Rv1 prostate cancer cells that express ERG-V5 from a stably integrated expression vector." (PMID 27626314, 2016). "Thus, overexpression of ERG in prostate cancer may cause an increase in TRIM25 activity, which is mitigated by the expression of the deubiquitinase USP9X, which is required to stabilize ERG." (PMID 27626314, 2016). "In a search for G3BP2-interacting proteins in prostate cancer LNCaP cells, RanBP2 and TRIM25 were among the top interacting factors." (PMID 39851496, 2025). "TRIM25 not only targets the 14-3-3 sigma, a known tumor suppressor of prostate cancer, for degradation by ubiquitination but it also mediates ISG15 modification of 14-3-3 sigma." (PMID 40723250, 2025). "In conclusion, our study developed a method, DMRG, to define important genes, and, combined with prostate cancer transcriptome data to define TRIM25, we clarified the role of TRIM25 in glucose metabolic reprogramming." (PMID 36012594, 2022). "This suggests that TRIM25 promotes malignancy in prostate cancer through the metabolic remodeling of glucose metabolism." (PMID 36012594, 2022). "Overexpression of TRIM25 is also known to promote cell proliferation and survival in prostate cancer." (PMID 33400740, 2020). "We demonstrated that TRIM25 knockdown results in increased ERG stability in TMPRSS2-ERG expressing prostate cancer cells." (PMID 27626314, 2016). "We examined the expression of TRIM25 protein by immunohistochemical analysis in 209 prostate cancer tumor samples that were placed on a tissue microarray generated at the University of Michigan." (PMID 27626314, 2016). "Our previous discovery of USP9X as an ERG-stabilizing deubiquitinase suggests that reduction of ERG protein levels by TRIM25-mediated proteasomal degradation is prevented by expression of USP9X in fusion-positive prostate cancer cells." (PMID 27626314, 2016). "Based on biological knowledge and prostate cancer transcriptome data, a tripartite motif-containing 25 (TRIM25) was defined using DMRG; TRIM25 was involved in the regulation of glucose metabolism, which was verified by overexpressing or knocking down TRIM25 in PCa cell lines." (PMID 36012594, 2022). "TRIM25 has not been implicated in prostate cancer biology, and no gain- or loss-of-function mutations for this gene have been reported for prostate cancer." (PMID 27626314, 2016). "We have identified TRIM25 as an ERG-binding ubiquitin ligase in prostate cancer cells." (PMID 27626314, 2016). "Meanwhile, TRIM25 and G3BP2 have previously been shown to interact in the context of prostate cancer." (PMID 36067236, 2022).